FTH1P8 (ferritin heavy chain 1 pseudogene 8)
Synonyms: formerly FTHL8
Gene: Processed pseudogene on chromosome X (148,052,233 to 148,052,746, forward strand). Ensembl gene ENSG00000219507.
Diseases named in the same sentence as FTH1P8 in open-access papers:
FTH1P8 is named in the same sentence as 1 disease in open-access papers, as found by Europe PMC text mining. Sharing a sentence is not in itself a finding about the gene and the disease. The quoted sentences say what the papers report.
prostate carcinoma (1 paper, 2019). A carcinoma that arises from epithelial cells of the prostate gland. "The FTH1 query also resulted in the identification of pseudogenes (FTH1P2, FTH1P8, FTH1P11, FTH1P16) that regulate FTH1 in prostate cancer as well novel miRNAs that may be involved in ceRNA network regulation of FTH1 in prostate cancer." (PMID 31029062, 2019).